AVP (arginine vasopressin)
Diseases named in the same sentence as AVP in open-access papers (continued):
Sharing a sentence is not in itself a finding about the gene and the disease.
arginine vasopressin deficiency (20 papers, 2010 to 2025). "In both arginine vasopressin deficiency and arginine vasopressin resistance, patients experience persistent diuresis, producing high volumes of dilute urine." (PMID 40291173, 2025). "AVP deficiency (AVP-D) is a rare endocrine disorder due to deficient AVP secretion, causing hypotonic polyuria and thirst." (PMID 41030530, 2025). "Upon arginine vasopressin challenge, urine osmolality increased by nearly 300%, suggesting complete arginine vasopressin deficiency." (PMID 40123924, 2025). "Arginine vasopressin deficiency (AVP-D) is a rare disorder resulting from reduced arginine vasopressin production, causing polyuria and thirst." (PMID 41030530, 2025). "Exposure to anaesthetic agents is a rare cause of self-limited but sudden and profound arginine vasopressin deficiency (AVP-D) or arginine vasopressin resistance (AVP-R)." (PMID 39475829, 2024). "Glucocorticoids inhibit AVP secretion and can unmask AVP deficiency in a patient with concomitant anterior and posterior pituitary dysfunction." (PMID 39475829, 2024). "Familial neurohypophyseal diabetes insipidus (FNDI) is characterized by a progressive decrease in AVP secretion caused by the degeneration of neurons in the hypothalamus." (PMID 36253431, 2022). "Most autosomal dominantly inherited cases of neurohypophyseal diabetes insipidus are due to AVP mutations located in the NPII moiety or in the signal peptide whereas few mutations are located directly in the AVP moiety." (PMID 34319541, 2021). "It results from either decreased secretion of AVP (AVP deficiency) or resistance to AVP action." (PMID 37859988, 2023). "Arginine infusion stimulates copeptin secretion, a surrogate marker of arginine vasopressin (AVP), thereby serving as a diagnostic test in the differential diagnosis of suspected AVP deficiency (AVP-D)." (PMID 39863827, 2025). "The differential diagnosis should include arginine vasopressin deficiency (AVD) and arginine vasopressin resistance (AVR)." (PMID 40870037, 2025). "Familial neurohypophyseal diabetes insipidus (FNDI) is a degenerative disease of vasopressin (AVP) neurons." (PMID 36253431, 2022). "G57S Pro-AVP is a mutant neuropeptide whose expression leads to an autosomal-dominant neurodegenerative disorder called neurohypophyseal diabetes insipidus (DI)." (PMID 34467852, 2021). "The pathway of Defective AVP does not bind AVPR2 causing neurohypophyseal diabetes insipidus (NDI); it is the most highlighted group term for down-regulated network." (PMID 32099601, 2019). "The absence of a 'relative vasopressin deficiency' may be one reason for the ineffectiveness of AVP in reducing norepinephrine requirements as compared with standard treatment with norepinephrine in the placebo group." (PMID 21054850, 2010).
Cirrhosis (20 papers, 2006 to 2025). A chronic disorder of the liver in which liver tissue becomes scarred and is partially replaced by regenerative nodules and fibrotic tissue resulting in loss of liver function. "The RAAS, SNS, and AVP play significant roles as part of these neurohormonal systems and lead to the progression of cirrhosis." (PMID 38202206, 2023). "AVP is increased in cirrhosis, especially in individuals who are hypo-responsive to water load, as assessed by water excretion via urine." (PMID 34070416, 2021). "Copeptin, the surrogate marker of AVP, is easily applicable in clinical practice and therefore interesting as a marker of hemodynamic derangement and prognosis in cirrhosis." (PMID 26378453, 2015). "AVP is metabolized by the kidney and the liver, and a reduced liver clearance can be anticipated in patients with cirrhosis." (PMID 26237020, 2014). "In patients with persistently low effective circulating volume (eg, chronic HF with reduced ejection fraction, advanced cirrhosis), sustained AVP secretion activates vasopressin receptor 1A, promoting myocardial remodeling and fibrosis, leading to increased morbidity and mortality." (PMID 40317183, 2025). "In advanced cirrhosis, maladaptive neurohormonal activation (increase in arginine vasopressin and renin–angiotensin–aldosterone system) leads to increased free water retention, which may result in reduced plasma concentrations of chloride." (PMID 33933032, 2021). "Plasma AVP levels are persistently elevated with augmented expression of AVP mRNA in the hypothalamus in liver cirrhosis, and its elevation is further manifested in decompensated cirrhosis as compared to compensated cirrhosis." (PMID 29088071, 2017). "Because of its key role in circulatory homeostasis and its systemic vasoconstrictor effects, AVP might be particularly interesting as a marker of circulatory dysfunction and prognosis in cirrhosis." (PMID 26378453, 2015). "Whenever arterial blood underfilling is encountered, in such opposite circumstances as “true hypovolemia” or so called “effective hypovolemia” a clinical picture commonly found in decompensated cirrhosis and congestive heart failure, AVP release is elicited, even if PNa is decreased." (PMID 26553121, 2015). "However, the assessment of the presence and impact of hemodynamic dysfunction in cirrhosis is complicated, due to the instability and poor reproducibility of potential biomarkers such as plasma norepinephrine, renin activity and AVP concentration." (PMID 26378453, 2015). "In advanced cirrhosis, hyperactivation of the neurohumoral axis, primarily represented by the SNS, the renin–angiotensin–aldosterone system (RAAS), and the consequent release of arginine vasopressin (AVP) occurs in response to excessive vasodilation of the splanchnic circulation." (PMID 39941227, 2025). "In patients with cirrhosis, as occurs in other clinical conditions such as chronic heart failure, nephrotic syndrome, and hypothyroidism, the most frequent explanation for the AVP hypersecretion is a nonosmotic stimulation related to systemic hemodynamic abnormalities." (PMID 26237020, 2014). "Acute glucose perfusion does not influence collateral AVP responsiveness, suggesting that long-term glycemic control is pivotal for improving the collateral vasocontractile response during variceal bleeding in cirrhosis." (PMID 23874439, 2013).
cyst (20 papers, 2012 to 2025). A sac-like closed membranous structure that may be empty or contain fluid or amorphous material. "When categorized by cyst content, AVP deficiency occurred in 44.0% of cases with pus-like mucous contents, compared to significantly fewer cases with transparent-mucous contents (9.4%)." (PMID 40585888, 2025). "Recent advances have linked cyst formation in ADPKD to arginine-vasopressin hormone (AVP)-signalling through the vasopressin V2-receptor and subsequent phosphodiesterase-driven cAMP modulation of that signal." (PMID 27899079, 2016). "In cases of intraoperative CSF leak, partial cyst wall resection can be attempted to mitigate the increased risk of recurrence associated with sellar reconstruction, but this must be balanced with the higher risk of AVP-deficiency." (PMID 40229623, 2025). "Intraoperative conversion to cyst wall resection may lower the recurrence risk, however, this must be balanced with the increased risk of AVP-deficiency." (PMID 40229623, 2025). "Elevated levels of the antidiuretic hormone, arginine vasopressin (AVP), in ADPKD patients have been associated with increased cyst growth and disease progression." (PMID 41030530, 2025). "Normally, AVP binds to V2 receptors in the distal nephron and collecting ducts, stimulating the production of cAMP, which drives cyst formation." (PMID 39339816, 2024). "Through the inhibition of the binding of the antidiuretic hormone arginine vasopressin (AVP) to its receptor, tolvaptan diminishes cAMP production and thus cAMP-associated cyst cell proliferation and cyst fluid secretion." (PMID 32630605, 2020). "Antidiuretic hormone arginine vasopressin promotes kidney-cyst cell proliferation and luminal fluid secretion by the up-regulation of its second messenger adenosine-3′,5′-cyclic monophosphate (cAMP)." (PMID 31752750, 2019). "Arginine vasopressin (AVP) is a hormone responsible for regulating water homeostasis and is the single most important endogenous factor potentiating cyst growth in ADPKD during the postnatal period." (PMID 30096903, 2018). "This increase in AVP can be harmful as AVP is known to enhance cell proliferation and cyst formation." (PMID 28081165, 2017). "When cysts are formed and expand because of a genetic defect, urine concentrating capacity decreases, leading to an increase in AVP and consequently to even more cyst formation and expansion." (PMID 28081165, 2017). "Studies have linked AVP-signalling through V2 receptors in the distal renal tubules and collecting ducts to a rise in intracellular cAMP-levels that in turn stimulates cyst growth by several mechanisms that may include chloride-driven fluid secretion from proliferating cyst-derived cells." (PMID 27899079, 2016). "It was shown to suppress plasma levels of arginine vasopressin in animal models of polycystic kidney disease, thereby slowing cyst progression." (PMID 23130747, 2012). "However, sustained increased levels of circulating AVP, a known cyst activator via the V2R and cAMP pathways, further promotes cystic pathways." (PMID 40763312, 2025). "Tolvaptan suppresses cyst growth by inhibiting arginine vasopressin (AVP)-mediated cAMP production." (PMID 40051696, 2025). "AVP binds to vasopressin 2 receptors (V2R) on kidney tubular epithelial cells, triggering a signaling cascade that leads to cyclic adenosine monophosphate (cAMP) production, which promotes cyst fluid secretion and stimulates cell proliferation." (PMID 41030530, 2025). "First, the trial of the conversion of cells from primed to naive state solved problems such as decreased survival, collapse of aggregates, and cyst formation by minimizing exogenous signals in the SFEBq method for the differentiation of human iPSCs into AVP neurons." (PMID 36253431, 2022). "On the other hand, water intake may suppress cyst fluid secretion through the inhibition of arginine vasopressin (AVP)-dependent cAMP synthesis." (PMID 30585217, 2018).
cyst (continued). "Recently, it has been demonstrated that the use of tolvaptan doses, likely to be attained in the plasma of ADPKD patients, inhibited AVP-induced proliferation through the B-Raf/MEK/ERK pathway and decreased both AVP-stimulated chlorine secretion and in vitro cyst growth of ADPKD cells." (PMID 36831539, 2023). "It is assumed that AVP has a detrimental role in ADPKD, because it leads to an increase in intracellular cAMP in distal tubular cells, which in turn leads to cell proliferation and increased fluid section, the processes that drive cyst formation and growth." (PMID 28081165, 2017). "Finally, cysts were induced with forskolin in a patient-derived UB organoid, although the cyst frequency was low and the effect of AVP was not reported." (PMID 40722835, 2025). "Based on the strong AVP deregulation observed in ADPKD and ARPKD animal models, strategic reduction of AVP-mediated signaling and intracellular cAMP using V2R antagonists was found to reduce both cystic fluid secretion and cyst size in murine PKD models and PKD patients." (PMID 33477721, 2021). "Cysts could also be induced with arginine vasopressin (AVP); however, the cyst frequency was very low, likely due to the lack of AVPR2 expression." (PMID 40722835, 2025).
small cell lung carcinoma (19 papers, 1999 to 2025). Small cell lung cancer (SCLC) is a highly aggressive malignant neoplasm, accounting for 10-15% of lung cancer cases, characterized byrapid growth, and early metastasis. "Ectopic secretion of arginine vasopressin by a tumor is often associated with small cell lung cancer but can also be seen in other neoplasms." (PMID 40584812, 2025). "We studied the effect of phenytoin on the release of copeptin, the C-terminal fragment of pro-AVP, and expression of AVP gene in the human small cell lung cancer cell line Lu-165." (PMID 28503166, 2017). "Small-cell lung cancer cells can also express the AVP gene as provasopressin, which remains attached to the cell membrane and conceivably contributes to the autocrine-driven mitogenesis." (PMID 15685238, 2005). "Schwartz's hypothesis was proven by detecting ectopic AVP in small cell carcinoma of the lung with inappropriate diuresis." (PMID 27635269, 2016).
congestive heart failure (18 papers, 2006 to 2025). Failure of the heart to pump a sufficient amount of blood to meet the needs of the body tissues, resulting in tissue congestion and edema. "AVP levels are elevated in patients with both acute and chronic heart failure, where it was shown to cause vasoconstriction, left ventricular remodeling, and water retention." (PMID 40217758, 2025). "It is plausible to speculate that TRPC3 inhibition might be instrumental in blocking excessive renal water retention during the clinically relevant states associated high AVP levels, such as congestive heart failure or syndrome of inappropriate AVP secretion." (PMID 31851715, 2019). "Elevated AVP levels have been observed in patients with congestive heart failure (CHF) and correlate with disease severity." (PMID 40428796, 2025). "Patients suffering from congestive heart failure (CHF) display high basal levels of AVP, which increases vascular smooth muscle tone." (PMID 33477721, 2021). "Copeptin (or pro-AVP) is a precursor of arginine vasopressin and is raised in a variety of diseases, including congestive heart failure." (PMID 31022834, 2019). "Cardiac output and plasma osmolality were significantly decreased and plasma AVP increased in the chronic heart failure rats compared to the sham-operated rats." (PMID 26239456, 2015). "Sustained AVP-dependent antidiuresis produces water retention, thus increasing the circulatory blood volume in congestive heart failure." (PMID 26239456, 2015). "A chronic stimulation of the vasopressin system that may contribute to AVP store depletion has been demonstrated in chronic heart failure." (PMID 22026977, 2011). "We examined plasma AVP levels and urinary excretion of AQP2 in 65 patients with congestive heart failure." (PMID 26239456, 2015). "Urinary excretion of AQP2 increased in the patients with congestive heart failure with higher NYHA class, and also had a significant positive correlation with plasma AVP levels." (PMID 26239456, 2015). "Admission serum Na levels had significant negative correlations with pulmonary capillary wedge pressure and with plasma AVP levels, thus indicating inappropriately the non-osmotic release of AVP in congestive heart failure." (PMID 26239456, 2015). "In chronic heart failure patients, renal salt and water homeostasis alterations are primarily driven by activation of the renin-angiotensin-aldosterone system and the non-osmotic release of arginine vasopressin." (PMID 40104143, 2025).
renal failure (17 papers, 2005 to 2025). "There are consistent suggestions that hypohydration and rehydration with fructose-based sweetened beverages facilitate the secretion of AVP and predispose humans to metabolic syndrome and the development of renal insufficiency." (PMID 35656391, 2022). "These factors include malnutrition, diuretics use, syndrome of inappropriate antidiuretic hormone secretion (SIADH), renal insufficiency, activation of the renin-angiotensin-aldosterone system, and increased arginine vasopressin (AVP)." (PMID 36415511, 2022). "Higher AVP levels and low hydration status worsen the renal insufficiency found in patients with metabolic syndrome." (PMID 35656391, 2022). "Arginine vasopressin (AVP) and its long-acting analogue terlipressin have been used to control variceal bleeding and hepatorenal syndrome." (PMID 23874439, 2013). "The ability to concentrate urine was decreased in renal insufficiency due to an impaired and reduced response in c-AMP and AQP2 to AVP, which was elevated in plasma, presumably as a compensatory phenomenon." (PMID 20923561, 2010). "The ability to dilute urine was deteriorated in renal insufficiency, presumably due to both a lack of suppression in AVP during water loading and a defect in the regulatory function of AVP on c-AMP with a secondarily up regulation of AQP2 water channels." (PMID 20923561, 2010).